IRAK4 (interleukin 1 receptor associated kinase 4)
Description:
Serine/threonine-protein kinase that plays a critical role in initiating innate immune response against foreign pathogens. Involved in Toll-like receptor (TLR) and IL-1R signaling pathways. Is rapidly recruited by MYD88 to the receptor-signaling complex upon TLR activation to form the Myddosome together with IRAK2. Phosphorylates initially IRAK1, thus stimulating the kinase activity and intensive autophosphorylation of IRAK1. Phosphorylates E3 ubiquitin ligases Pellino proteins (PELI1, PELI2 and PELI3) to promote pellino-mediated polyubiquitination of IRAK1. Then, the ubiquitin-binding domain of IKBKG/NEMO binds to polyubiquitinated IRAK1 bringing together the IRAK1-MAP3K7/TAK1-TRAF6 complex and the NEMO-IKKA-IKKB complex. In turn, MAP3K7/TAK1 activates IKKs (CHUK/IKKA and IKBKB/IKKB) leading to NF-kappa-B nuclear translocation and activation. Alternatively, phosphorylates TIRAP to promote its ubiquitination and subsequent degradation. Phosphorylates NCF1 and regulates NADPH oxidase activation after LPS stimulation suggesting a similar mechanism during microbial infections.
Synonyms: IRAK-4; NY-REN-64; IMD67; IPD1; REN64
Tractability: Small molecule: a drug acting on it is in phase 2 or 3 trials; a structure with a bound ligand is known; a high-quality ligand is known; it has a high-quality binding pocket; it belongs to a druggable protein family. Antibody: its Gene Ontology location is reachable by antibodies, with high confidence. PROTAC: a drug acting on it is in phase 1 trials; it is named in the literature on targeted protein degradation; ubiquitination databases record sites on it; its protein half-life has been measured; a small molecule that binds it is known.
Target class: Kinase; TKL protein kinase IRAK family; TKL protein kinase group; Enzyme; Protein Kinase
Chemical probes: BI1543673 (high quality), CHEMBL3601192, IRAK4 inhibitor rac-45, IRAK4-IN-28 (high quality), IRAK4i-2 (high quality), PD081468, PD081809, PD083946, PD084254, PF-06650833 (high quality), emavusertib (high quality)
Gene: Protein-coding gene on chromosome 12 (43,758,944 to 43,798,307, forward strand). Ensembl gene ENSG00000198001.
Subcellular location: Cytoplasm
Subcellular location (Human Protein Atlas): Cytosol; Microtubules; Nucleoli; Plasma membrane
Pathways (Reactome):
Immune System: Interleukin-1 signaling; MyD88 cascade initiated on plasma membrane; MyD88 dependent cascade initiated on endosome; MyD88:MAL(TIRAP) cascade initiated on plasma membrane; TRAF6 mediated IRF7 activation in TLR7/8 or 9 signaling; TRAF6 mediated induction of NFkB and MAP kinases upon TLR7/8 or 9 activation
Disease: IRAK4 deficiency (TLR2/4); IRAK4 deficiency (TLR5)
Signal Transduction: PI5P, PP2A and IER3 Regulate PI3K/AKT Signaling; PIP3 activates AKT signaling
Gene Ontology:
Molecular function: kinase activity; protein binding; protein kinase binding; protein serine/threonine kinase activity; ATP binding; interleukin-1 receptor binding; magnesium ion binding; protein kinase activity; protein serine kinase activity
Biological process: interleukin-1-mediated signaling pathway; interleukin-33-mediated signaling pathway; neutrophil mediated immunity; neutrophil migration; positive regulation of canonical NF-kappaB signal transduction; toll-like receptor 9 signaling pathway; canonical NF-kappaB signal transduction; cytokine-mediated signaling pathway; innate immune response; intracellular signal transduction; lipopolysaccharide-mediated signaling pathway; MyD88-dependent toll-like receptor signaling pathway; NLRP3 inflammasome complex assembly; regulation of MAP kinase activity; Toll signaling pathway; toll-like receptor 4 signaling pathway; toll-like receptor signaling pathway; JNK cascade; positive regulation of smooth muscle cell proliferation; signal transduction
Cellular component: cell surface; cytosol; cytoplasm; endosome membrane; extrinsic component of plasma membrane; plasma membrane; serine/threonine protein kinase complex; extracellular region
Genetic constraint (gnomAD): Loss-of-function variants: 27 observed, 31.69 expected, observed/expected ratio (o/e) 0.85, 90% interval 0.63 to 1.17. The upper end of that interval is the gene's LOEUF score, 1.17, which puts it in group 5 of 6, group 1 being the genes least tolerant of losing a copy. Missense variants: 341 observed, 406.63 expected, observed/expected ratio (o/e) 0.84, 90% interval 0.77 to 0.92. Synonymous variants: 108 observed, 138.63 expected, observed/expected ratio (o/e) 0.78, 90% interval 0.67 to 0.91.
Homologues: Orthologues: chimpanzee IRAK4 (99% identical), macaque IRAK4 (99% identical), pig IRAK4 (90% identical), rabbit IRAK4 (88% identical), guinea pig IRAK4 (87% identical), rat Irak4 (84% identical), dog IRAK4 (84% identical), mouse Irak4 (84% identical), tropical clawed frog irak4 (59% identical), zebrafish irak4 (45% identical). Paralogues in human: IRAK1 (30% identical), IRAK2 (26% identical), IRAK3 (25% identical), HASPIN (17% identical).
Diseases named in the same sentence as IRAK4 in open-access papers:
IRAK4 is named in the same sentence as 168 diseases in open-access papers, as found by Europe PMC text mining. Sharing a sentence is not in itself a finding about the gene and the disease. The quoted sentences say what the papers report.
autoimmune disease (21 papers, 2016 to 2025). A disorder resulting from loss of function or tissue destruction of an organ or multiple organs, arising from humoral or cellular immune responses of the individual to their own tissue constituents. "IRAK4 kinase has been reported to be closely associated with inflammatory and autoimmune diseases, and several IRAK4 inhibitors have been used in the study of such disorders." (PMID 38675622, 2024). "Interleukin-1 receptor-associated kinase 4 (IRAK4) is a key protein in the immune response mediated by toll-like receptors and interleukin receptors and has been identified as an autoimmune disease and cancer dual target." (PMID 36142231, 2022). "The hyperactivation of interleukin-1 receptor-associated kinase 4 (IRAK4), a key mediator of innate immunity, is linked with autoimmune diseases and cancer." (PMID 32718354, 2020). "The loss of kinase function of IRAK4 is associated with increased susceptibility to various pathogens, while its over-activation causes autoimmune diseases such as rheumatoid arthritis, systemic lupus erythematosus, and cancer." (PMID 27845762, 2016). "Loss of IRAK4 function can impair normal inflammatory responses, increasing susceptibility to severe bacterial infections, while hyperactivation may trigger autoimmune diseases." (PMID 41220927, 2025). "Recent studies have shown that IRAK4 is associated with some autoimmune diseases." (PMID 33465375, 2021). "Early-phase trials explored the potential of targeting proteins like IKZF1/3 in multiple myeloma and IRAK4 in autoimmune diseases." (PMID 40574056, 2025). "Our study shows that an oral IRAK4 degrader in development for TLR/IL-1R–driven autoimmune diseases has robust in vivo activity against the target and pathway in HVs and patients, with a favorable safety and tolerability profile." (PMID 37957373, 2023). "KT-474 (SAR444656) is a selective small-molecule degrader of IRAK4 in development for the treatment of TLR/IL-1R–driven autoimmune diseases." (PMID 37957373, 2023). "PF-0665033 was the first IRAK4 inhibitor to enter clinical development, and it is tested in clinical trials for rheumatic and autoimmune diseases." (PMID 34572504, 2021). "Over 90 patents for small molecule IRAK4 inhibitors have been filed from 2016 to 2018, primarily for autoimmune diseases and cancer." (PMID 31354711, 2019). "For the first time, we show the effects of an IRAK4 inhibitor on both transcription and protein synthesis in RNA-IC-activated pDCs, which demonstrates that IRAK4 inhibition affects many cellular pathways of importance in an autoimmune disease process." (PMID 30355354, 2018). "AS-2444697, PF-05387252, PF-05388169, and PF-06650833 target the kinase activity of IRAK4 and have been investigated in preclinical or clinical studies for the treatment of multiple inflammatory and autoimmune diseases, including gout, sepsis, AR, and SLE." (PMID 28894754, 2017). "Although IRAK4 is an important and interesting therapeutic target to treat inflammatory and autoimmune diseases, identification and development of selective inhibitors is challenging." (PMID 27845762, 2016). "Notably, a couple of IRAK4 inhibitors have been employed in the clinical treatment of inflammation and autoimmune diseases." (PMID 38675622, 2024). "IRAK4 is a one of the important serine/threonine kinases that play fundamental role in cell signaling, inflammation, apoptosis, and cellular differentiation, which makes it an ultimate drug target for several types of cancers and autoimmune diseases." (PMID 36234844, 2022). "That is the case in some neurodegenerative diseases or in conditions where degradation of a protein could have major impact than its enzymatic inhibition, as in the case of IRAK4 targeting in autoimmune diseases." (PMID 32933565, 2020). "Our findings suggest that the scaffold function of IRAK4 may be an attractive target for treating inflammatory and autoimmune diseases." (PMID 30076215, 2018).
autoimmune disease (continued). "In the field of autoimmune diseases, KT-474, developed by Kymera Therapeutics, is currently in Phase 1 trials as a PROTAC targeting IRAK4." (PMID 40574056, 2025). "Therefore, IRAK4 has a vital role in innate immunity and its inhibition by small molecules would be significant for the treatment of various types of inflammations and autoimmune disease such as inflammatory bowel disease (IBD), rheumatoid arthritis (RA) and Systematic Lupus Erythematosus (SLE)." (PMID 36234844, 2022). "Other small molecular weight chemical compounds that inhibit TLR signaling and TLR-mediated inflammatory responses in autoimmune diseases include SM934, ST-2825, IRAK4 inhibitors, and IKK2 inhibitors." (PMID 28894754, 2017). "IRAK4-targeted PROTACs can eliminate both enzymatic and non-enzymatic functions of IRAK4, and due to better cellular penetration in immune cells compared to solid tumors, they represent a promising new strategy for autoimmune disease therapy." (PMID 41220927, 2025). "IRAK4 is a critical mediator in NF-κB-regulated inflammatory signaling and has emerged as a promising therapeutic target for the treatment of autoimmune diseases; however, none of its inhibitors have received FDA approval." (PMID 38675622, 2024). "While patients with IRAK4 deficiency accumulate autoreactive B cells in the blood, the inhibition of the TLR signaling pathway is unlikely to develop autoimmune disorders." (PMID 33083971, 2021). "Similarly, IRAK4 inhibitors, ND-2158 and ND-2110 attenuated TNFα production from TLR4/9-stimulated human PBMCs and autoimmune disease in collagen-induced arthritis and gout murine models." (PMID 31354711, 2019). "IRAK4- or MyD88-deficient patients suffer from bacterial or viral infections but not from autoimmune diseases, suggesting that targeting of IRAK4 and MyD88 may prevent autoimmunity in humans." (PMID 34572504, 2021).
lupus (18 papers, 2009 to 2025). "Recent data show that the expression of TLR7 in mild and severe lupus-prone models is dependent on the activity of IRAK4 (the TLR7-downstream signaling molecule) and the pathogenic environment." (PMID 35309296, 2022). "Impairments of IRAK4 signaling refrain from all pathological characteristics associated with murine lupus." (PMID 35309296, 2022). "IRAK4 has thus emerged as an attractive therapeutic target for diseases associated with dysregulated inflammation, such as systemic lupus erythematosus (SLE), rheumatoid arthritis (RA), spondylarthritis, and psoriatic arthritis." (PMID 34248990, 2021). "MyD88 forms oligomeric complexes with members of the IL-1 receptor-associated kinases (IRAKs), termed the Myddosome, and lupus in ABIN1[D485N] mice is also prevented by crossing to mice in which IRAK4 or IRAK1 are replaced by kinase-inactive mutants." (PMID 31694920, 2019). "Elimination of IRAK4 signaling prevented all pathological traits associated with murine lupus, including splenomegaly with leukocyte expansion, detectable circulating antinuclear antibodies and glomerulonephritis, in both Sle1 and Sle1Tg7 mice." (PMID 31354711, 2019). "Autoinflammation has never been described in association with mutations in IRAK4, although upregulation of IRAK-4 has been implicated in inflammation in murine models of lupus and rheumatoid arthritis, which has led to the development of novel selective IRAK-4 inhibitors." (PMID 37744344, 2023). "Moreover, it is important to know if these suppressive effects of IRAK4 elimination on TLR7-dependent lupus-traits are due to the loss of susceptibility loci resulting from the introduction of B6-nonautoimmune background into the F2 progeny." (PMID 31354711, 2019). "Using a pre-clinical NPSLE model, we compare lupus-like B6.MRL-Faslpr (MRL) mice with B6.MRL-Faslpr-IRAK4 kinase-dead (MRL-IRAK4-KD) mice, which are were less prone to ‘general’ lupus-like symptoms." (PMID 39014006, 2024). "The contextual linking words indicate why the model suggested IRAK4 for lupus, due to its involvement in innate immunity through TLR7 that subsequently activates Myd8841,42." (PMID 37225853, 2023). "Other pathways involved in lupus pathogenesis, such as tyrosine kinase 2 (TYK2) and serine/threonine kinase IL-1R–associated kinase (IRAK4), represent potential future therapeutic targets of interest." (PMID 35899214, 2022). "In keeping with the data from lupus mice shown here and by others, the IRAK4 inhibitor BMS-986126 suppressed the development of lupus in the NZB/NZW and MRLlpr models." (PMID 31354711, 2019). "This article shows that liver and kidney damage in a lupus-prone mouse line occurs by different mechanisms and that only drugs targeting core components of signaling pathway, such as IRAK4, are able to suppress all facets of the disease." (PMID 31694920, 2019). "We demonstrate that lupus-prone mice with a mutation in the kinase domain of IRAK4 no longer display typical lupus hallmarks such as splenomegaly, inflammation, production of hormones, and anti-double-stranded (ds)DNA antibody." (PMID 39014006, 2024). "We found that every facet of the lupus phenotype could be prevented by crossing ABIN1[D485N] mice to MyD88 KO mice or to mice expressing kinase-inactive mutants of IRAK4 or IRAK1." (PMID 31615747, 2020). "Because the other components of the Myddosome are IRAK1 and IRAK4 and the inactive pseudokinase IRAK2, we studied whether the loss of IRAK1 or IRAK4 catalytic activity, or IRAK2 function, prevented lupus in ABIN1[D485N] mice." (PMID 27807192, 2016). "These considerations suggest that only drugs targeting a core component of the MyD88-IRAK4-IRAK1 pathway will have the potential to suppress all facets of the lupus phenotype and led us to treat the ABIN1[D485N] mice with an orally active IRAK4 inhibitor." (PMID 31694920, 2019).
lupus (continued). "The involvement of IRAK-4 in TLR7 and TLR9 signaling, coupled with the observation that dual inhibition of TLR7 and TLR9 in lupus-prone mice results in amelioration of disease symptoms, indicates that IRAK-4 may be a suitable therapeutic target for systemic lupus erythematosus (SLE)." (PMID 19689377, 2009).
rheumatoid arthritis (18 papers, 2009 to 2025). A chronic, systemic autoimmune disorder characterized by inflammation in the synovial membranes and articular surfaces. "Previous studies have shown that abnormal IRAK4 activity is linked not only to cancer but also to inflammatory diseases, including sepsis, psoriasis, systemic lupus erythematosus, and rheumatoid arthritis." (PMID 40771916, 2025). "In summary, IRAK4 appears to be indispensable inTLR/IL-1R signaling,and activation of the IRAK4 pathway is associated with inflammatoryand autoimmune disorders such as atopic dermatitis, lupus erythematosus,hidradenitis suppurativa, and rheumatoid arthritis." (PMID 38228402, 2024). "The IRAK4 inhibitor zimlovisertib, for example, showed positive proof of concept in a phase 2b trial in patients with active rheumatoid arthritis." (PMID 40520205, 2025). "Nonetheless, the representative IRAK4 inhibitor PF-06650833 for clinical rheumatoid arthritis treatment was withdrawn or terminated." (PMID 40771916, 2025). "Although developed recently, IRAK4 inhibitors are under assessment in psoriasis, whilst in rheumatoid arthritis a completed phase II clinical trial has demonstrated clinical improvement." (PMID 33936053, 2021). "An IRAK4 inhibitor, Pf-06650833, is in clinical development in refractory rheumatoid arthritis (NCT02996500)." (PMID 30279971, 2018). "Owing to its role in TLR signaling, IRAK4 is involved in the release of several inflammatory cytokines and chemokines; therefore, hyperactivity of IRAK4 signaling can ultimately lead to several inflammatory disorders such as rheumatoid arthritis and inflammatory bowel disease." (PMID 38138875, 2023). "In addition, several pharmaceutical companies are currently testing different small-molecule inhibitors of IRAK4 as potential drugs against rheumatoid arthritis, inflammatory bowel disease, and hematologic malignancies." (PMID 38138875, 2023). "Our studies have shown that the onset of rheumatoid arthritis (RA) is abrogated by the inhibition of IRAK4 in TLR7-induced inflammation in macrophage and fibroblast cell-based and in vivo models of joint inflammation." (PMID 40709261, 2025). "It showed that IRAK4 could antagonize inflammatory osteolysis, and IRAK4 inhibitor (IRAK4i) therapy attenuated rheumatoid arthritis (RA) disease activity by blocking M1 macrophage activation and also disrupted osteoclastogenesis." (PMID 37158847, 2023). "An orally bioavailable heterobifunctional IRAK4 degrader (KT-474) in phase I clinical trials (NCT04772885) could treat patients with various immuno-inflammatory diseases, such as rheumatoid arthritis, atopic dermatitis or hidradenitis suppurativa." (PMID 36499765, 2022). "All of these data suggest that IRAK-4 may be a suitable target for inflammatory diseases involving multiple receptors including IL-1R (rheumatoid arthritis (RA) and osteoarthritis (OA)), IL-18R (inflammatory bowel disease (IBD)), TLR2, 4 (RA), and TLR7, 9 (SLE)." (PMID 19689377, 2009).